TUBB2A (tubulin beta 2A class IIa)
Diseases named in the same sentence as TUBB2A in open-access papers (continued):
Sharing a sentence is not in itself a finding about the gene and the disease.
tumor (12 papers, 2014 to 2026). "Of the 2 protein targets, the result showed that the TUBB2A has association with the proliferation of tumor/carcinoma cell lines, microtubule-based processes, epithelial adherens junction signaling, 14-3-3-mediated signaling, and phagosome maturation." (PMID 32489334, 2020). "The most down regulated protein identified in HEY Oct4A KD xenograft tumor samples was the cytoskeleton-associated protein TUBB2A (Rsc −78.1)." (PMID 28406185, 2017). "The most significant function of TUBB2A was cell proliferation of tumor cell lines (p-value = 1.69E−08)." (PMID 32489334, 2020). "TUBB2A might control the migration of BC cells from a primary tumor to distant metastatic sites by regulation of the adhesion and proliferation of BC cells." (PMID 36500393, 2022). "Elevated TUBB2A expression correlated with higher AFP levels, microvascular invasion, advanced tumor stages, and poorer overall survival." (PMID 41918784, 2026). "We therefore combined methylation data from patient tumor tissues and cell lines following decitabine treatment to converge on six genes (CRIP1, G0S2, MLH1, OPN3, S100 and TUBB2A) as the classifier." (PMID 25391133, 2014). "Analyzing expression profile of BC tumors and tumor-adjacent normal breast tissues showed upregulation of TUBA1A, TUBA1C, TUBB and TUBB3 and downregulation of TUBB2A, TUBB2B, TUBB6, TUBB7P pseudogene, and TUBGCP2 in the tumor tissues compared to the normal breast tissues." (PMID 30126203, 2018).
cancer (11 papers, 2011 to 2025). A tumor composed of atypical neoplastic, often pleomorphic cells that invade other tissues. "And additional research is required to clarify the regulatory relationships and underlying mechanisms of SSBP1, RPA3 and TUBB2A in Cancer cell lactylation despite demonstrating an association between them." (PMID 40642071, 2025). "We divided cancer cells into six groups: SSBP1+ cancer group, SSBP1− cancer group, RPA3+ cancer group and RPA3− cancer group, TUBB2A+ cancer group and TUBB2A− cancer group." (PMID 40642071, 2025). "The proportion of SSBP1, RPA3, and TUBB2A cancer cells increased synchronously during the quasi-time course." (PMID 40642071, 2025). "Another study showed that TUBB2A overexpression promoted the formation of filopodia, which are involved in cancer cell migration and invasion." (PMID 38891892, 2024). "TUBB2A has been identified as a potential target for cancer therapy due to its role in cancer progression." (PMID 38891892, 2024). "The precise mechanism by which TUBB2A promotes cancer progression is still under investigation." (PMID 38891892, 2024). "Targeting TUBB2A may represent a promising approach for cancer therapy." (PMID 38891892, 2024). "Notably, IPA analysis identified 12 of the ERβ-interacting proteins as having roles in cancer progression and metastasis with 4 of these proteins having established roles in NSCLC, i.e., EEFIA, MYL12A, TUBB2A, VIM1." (PMID 21951318, 2011).
infection (3 papers, 2019 to 2022). The state of being infected such as from the introduction of a foreign agent such as serum, vaccine, antigenic substance or organism. "The analysis also identified four tubulin genes (Tubb2A, Tubb2b, Tubb3 and Tubb4B) which have previously been associated with E. coli pathogenesis, to be up-regulated in the asymptomatic (resilient to infection) dataset." (PMID 30709726, 2019).
neurodegenerative disease (2 papers, 2023 to 2024). A disorder of the central nervous system characterized by gradual and progressive loss of neural tissue and neurologic function. "The results showed that the single-cell samples of the CA1 subregion were mainly involved in vesicle-mediated transport in synapse and neurodegenerative disease-related functions, and Syn2, Sh3gl2, Aldoa, Tubb2a and Eno1 were screened as the key target genes." (PMID 36768134, 2023).
neurodevelopmental disorder (2 papers, 2023 to 2024). A behavioral and cognitive disorder with onset during the developmental period that involves impaired or aberrant development of intellectual, motor, or social functions. "Although tubulinopathies usually include neurodevelopmental disorders, mutations in TUBB2A and TUBA4A may also underlie neurodegenerative disorders." (PMID 37418012, 2023). "Mutations in genes encoding for tubulin subunits (TUBA1A, TUBB2B, TUBB3, TUBB2A, TUBB5, and TUBG1) have been associated with a broad spectrum of neurodevelopmental disorders, usually transmitted in an autosomal dominant manner and mostly characterized by non-progressive complex brain malformations." (PMID 37418012, 2023).
peripheral neuropathy (1 paper, 2015). A disorder affecting the peripheral nervous system. "Paclitaxel binds to β-tubulin to exert its cytotoxic effect and genetic variants within the promoter of TUBB2A have previously been shown to be associated with increased expression of the gene and reduced risk of paclitaxel-induced peripheral neuropathy." (PMID 25689802, 2015).
TUBB2A also shares sentences with these, for which no sentence is quoted: epilepsy (3 papers); Intellectual disability (3); glioblastoma (2); glioma (2); Leukoencephalopathy (2); Lissencephaly (2); neurological disorders (2); autism (1); axonal neuropathy (1); brain tumor (1); cardiomyopathy (1); cerebellar agenesis (1); congenital myasthenic syndrome (1); E. coli infection (1); Epileptic encephalopathy (1); frontotemporal dementia (1); hearing loss (1); hepatocellular carcinoma (1); HIV-1 infection (1); Immunodeficiency 50 (1); kidney diseases (1); Lewy Body Disease (1); liver cancer (1); lung carcinoma (1); Macrogyria (1); metastatic tumors (1); microlissencephaly (1); neuroblastoma (1); Niemann-Pick disease (1); non-small cell lung carcinoma (1).
A further 10 diseases each share a sentence with TUBB2A in 1 paper.